ANXA2 (annexin A2)
Diseases named in the same sentence as ANXA2 in open-access papers (continued):
Sharing a sentence is not in itself a finding about the gene and the disease.
breast carcinoma (continued). "Our previous work revealed Annexin A2 to be a newly synthesized protein in the growth factor induced migration and invasion of breast cancer cells." (PMID 37941562, 2023). "The contradiction between the experimental results and the bioinformatics analysis results needs to be verified by deeper experiments or more datasets, which will enable us to better understand the role of ANXA2 in breast cancer." (PMID 36713082, 2023). "Our results indicated that AQP1, ANXA2, and Rab1b formed a ternary complex in the Golgi apparatus to induce breast cancer local invasion." (PMID 36803413, 2023). "We have previously shown that Annexin A2 is integral in the migration and invasion of breast cancer cells and in the clinical progression of ER-negative breast cancer, processes which are highly influenced by the surrounding tumor microenvironment and ECM." (PMID 37941562, 2023). "Remarkably, we saw that knockdown of Annexin A2 did in fact impair the fibronectin degradation ability of MDA-MB-231 breast cancer cells." (PMID 37941562, 2023). "Collectively, these findings revealed that AQP1 interacted with ANXA2 to promote Golgi apparatus extension through F-actin, inducing breast cancer cell invasion." (PMID 36803413, 2023). "Co-immunoprecipitation, immunofluorescence assays and cell functional experiments were carried out to define the relationship among AQP1, ANXA2 and Rab1b and their re-localization in breast cancer cells." (PMID 36803413, 2023). "Previous studies reported that ANXA2 was significantly elevated in tumor issues and related to poor prognosis in breast cancer, glioma, gastric cancer and liver cancer." (PMID 35205125, 2022). "Upregulation of AnxA2 has been observed in gastric cancer, endometrial cancer, pancreatic ductal adenocarcinoma, hepatocellular carcinoma, breast cancer, kidney renal clear cell carcinoma, high-grade prostate cancer, and glioblastoma." (PMID 36428758, 2022). "To confirm this finding, we first identified ANXA2 as a 38 kDa protein present at similar levels in ERα+ and ERα− breast cancer cells." (PMID 34240826, 2022). "ANXA2 (green) displayed cytoplasmic as well as nucleolar staining patterns in all tested breast cancer cell lines, both in ERα+ and ERα− cells." (PMID 34240826, 2022). "This study presents a novel finding that ANXA2 is an interacting partner of EpCAM in the EpCAM+ ERα+ breast cancer cells, and co‐localizes with EpCAM at the plasma membrane of EpCAM+ ERα+ breast cancer cells." (PMID 34240826, 2022). "The assessment of the protein levels of ANXA2 and EpCAM relative to GAPDH showed that ANXA2 is expressed in all breast cancer cell lines whilst EpCAM is expressed only in the ERα+ cells ZR‐75‐1 and MCF‐7." (PMID 34240826, 2022). "Annexin A2 from breast cancer exosomes can stimulate the secretion of IL-6 and TNF-α by inducing macrophage-mediated p38 MAPKs." (PMID 34485600, 2021). "ANXA2 has been reported to be involved in breast cancer neoangiogenesis, invasiveness, and resistance." (PMID 34771120, 2021). "Annexin A2 in exosomes secreted by human breast cancer cells increases plasminogen production through the tPA-dependent pathway, thereby stimulating angiogenesis." (PMID 34485600, 2021). "In recent years, Maji and colleagues investigated the role of exosomal AnxA2 (exo-AnxA2) in breast cancer metastasis." (PMID 34359598, 2021). "Upregulated ANXA2 was associated with the inhibited BAG2 signaling pathway, which is usually highly abundant in breast cancer and promotes tumor progression and metastasis." (PMID 34771120, 2021). "AnxA2 and AnxA6, expressed on the cell surface, were shown to serve as receptors for adhesion to immobilized FetuA in breast carcinoma cells." (PMID 33924370, 2021). "Annexin A2 was also found to be significantly elevated in the plasma of breast cancer patients compared with healthy controls." (PMID 33406648, 2021).
breast carcinoma (continued). "The same results were observed in other cancers: The down-regulation of ANXA2 in lung cancer cell line A54918 or breast cancer cell line MDA-MB-23119 significantly reduced the proliferation capacity of tumor cells." (PMID 33658625, 2021). "In breast cancer, intra- and extracellular AnxA2 activities and locations, including exosomes, have become promising therapeutic targets." (PMID 33810523, 2021). "Previously, ANXA2 was identified as an independent prognostic marker in several cancer types, including laryngeal cancer, breast cancer, ovarian cancer and endometrial cancer." (PMID 34575275, 2021). "P-glycoprotein interacted with ANXA2 and that both P-glycoprotein and ANXA2 expression were highly expressed in adriamycin-resistant breast cancer cell lines." (PMID 34048174, 2021). "Anxa2, acting as an NF-κB co-activator in hepatocellular carcinoma and pancreatic cancer, was first identified bound to p50 subunit of NF-κB in breast cancer cells." (PMID 32244350, 2020). "Based on molecular subtypes of breast cancer specimens, strong staining of AnxA2 was predominantly observed with only triple-negative subtypes of breast cancer specimens (54.54%, n = 18) compared with other breast cancer subtypes (p < 0.0001)." (PMID 33374917, 2020). "Together, these data suggest that AnxA2 plays a pivotal role in breast cancer invasion and angiogenesis." (PMID 32575495, 2020). "We saw that high serum AnxA2 group was associated with worse DFS (Hazard ratio: 8.160; 95% CI = 1.824–36.501; log-rank test p = 0.001) in breast cancer patients." (PMID 33374917, 2020). "We used the median expression value for serum exo-AnxA2 in breast cancer patients (n = 169) to stratify into a high exo-AnxA2 (> 77.87 ng/mL) and a low exo-AnxA2 groups (< 77.87 ng/mL)." (PMID 31992335, 2020). "ANXA2 has been reported to affect breast cancer cell proliferation and invasion via activation of the ERK1/2 signaling pathway." (PMID 32248843, 2020). "Emerging evidence shows that AnxA2 is upregulated and correlated to poor prognosis in patients with breast cancer." (PMID 31992335, 2020). "Western blot analysis show that EpCAM-positive breast cancer exosomes express AnxA2 and exosomal markers CD9, TSG101, and flotillin-1." (PMID 31992335, 2020). "Here, we show that the expression of exo-AnxA2 is elevated in the sera of the breast cancer patients and plays an important role in angiogenesis." (PMID 31992335, 2020). "In the present study, we analyzed the expression of AnxA2 in tumor tissues of different subtypes of breast cancer patients and normal breast tissues." (PMID 33374917, 2020). "In our previous studies, we have shown that AnxA2 is overexpressed in TNBC in comparison to other subtypes of breast cancer." (PMID 31992335, 2020). "A Kaplan–Meier curves were used to analyze the prognostic role of serum AnxA2 levels in breast cancer patients." (PMID 33374917, 2020). "Our approach has added to the consensus that Annexin A2 plays an important role in the progression of breast cancer, suggesting that stimulus to migrate and invade with an EGF chemoattractant actually induces the nascent translation of Annexin A2." (PMID 32629869, 2020). "In conclusion, our results demonstrated the several applications of serum AnxA2 concentrations in breast cancer patients in a non-invasive procedure." (PMID 33374917, 2020). "Annexin A2 was identified in this screen and subsequent examination of breast cancer cell lines revealed that Annexin A2 is specifically upregulated in estrogen receptor negative (ER-) cell lines." (PMID 32629869, 2020). "The median expression value of serum AnxA2 was categorized as a threshold to divide the breast cancer patients (n = 162) into two groups: high serum AnxA2 group (>10.11 ng/mL; n = 81) and low AnxA2 (<10.11 ng/mL; n = 81) group." (PMID 33374917, 2020). "Altogether, these studies suggest the potential role of circulating AnxA2 in the diagnosis and prognosis of breast cancer patients." (PMID 33374917, 2020).
breast carcinoma (continued). "Our results show that the expression of serum exo-AnxA2 in breast cancer patients (n = 169; 83.33 ± 2.040 ng/mL, P < 0.0001) is high compared to non-cancer females (n = 68; 34.21 ± 2.238 ng/mL)." (PMID 31992335, 2020). "The results of the present study further confirm that serum AnxA2 concentrations were elevated in breast cancer patients compared to normal healthy females." (PMID 33374917, 2020). "Annexin A2 (AnxA2) is a Ca++-dependent phospholipid-binding protein that is involved in invasion and metastasis of breast cancer." (PMID 33374917, 2020). "In the extracellular environment, AnxA2 secretion is correlated with the invasive phenotype of the breast cancer cells." (PMID 33374917, 2020). "The expression of AnxA2 in cell lines, tumor tissues, and serum samples of breast cancer patients were analyzed by immunoblotting, immunohistochemistry, and enzyme-linked immunosorbent assay, respectively." (PMID 33374917, 2020). "Our work has used innovative models to add substantial weight to the findings by others, linking Annexin A2 to breast cancer." (PMID 32629869, 2020). "It was previously reported that the expression of AnxA2 increases with the aggressiveness of breast cancer." (PMID 33374917, 2020). "ELISA analysis shows that exo-AnxA2 concentration was significantly elevated in serum samples of breast cancer patients (n = 169, 83.33 ± 2.040 ng/mL, P < 0.0001) in comparison to non-cancer (n = 68, 34.21 ± 2.238 ng/mL) females." (PMID 31992335, 2020). "In our study, the Kaplan–Meier method was performed to analyze the relationship between serum exo-AnxA2 levels and OS of patients with breast cancer." (PMID 31992335, 2020). "In fact, AnxA2 expression has been identified as a potential biomarker for metastatic recurrence of breast cancer." (PMID 33374917, 2020). "Next, we examined Annexin A2 mRNA expression using RT-qPCR in breast cancer cell lines, under normal, serum starved and EGF stimulated conditions." (PMID 32629869, 2020). "As well as successfully identifying Annexin A2 as a mediator of breast cancer cell migration and invasion, our screen has provided an extensive list of proteins potentially involved in breast cancer metastasis which require further investigation." (PMID 32629869, 2020). "Our analysis showed that AnxA2 levels were significantly high in serum samples of breast cancer patients (n = 162; 11.18 ± 0.505 ng/mL, p < 0.0001) compared to normal healthy females (n = 65; 6.616 ± 0.544 ng/mL)." (PMID 33374917, 2020). "This work establishes a pivotal role of Annexin A2 in breast cancer progression and identifies Annexin A2 as a potential therapeutic target for the more aggressive and harder to treat ER- subtype." (PMID 32629869, 2020). "The area under the curve (AUC) for the ROC curve of the test with exo-AnxA2 levels in serum samples of breast cancer patients as the disease indicator was 0.9484 ± 0.01327 (95% CI = 0.9223–0.9744, P < 0.0001)." (PMID 31992335, 2020). "The results of the present study in addition to our previous findings showed that AnxA2 is abundantly expressed in triple-negative subtypes of breast cancer at mRNA and protein levels." (PMID 33374917, 2020). "We found that high serum exo-AnxA2 levels (n = 54) were associated with worse DFS (hazard ratio 7.934; 95% CI = 1.778–35.398; log-rank P = 0.0301) in breast cancer patients (n = 53)." (PMID 31992335, 2020). "Overexpression of annexin A2 has been observed in many malignancies, including aggressive breast cancer." (PMID 32575495, 2020). "Through this we found, in support of our argument, that Annexin A2 expression at the level of the protein is significantly higher in ER- breast cancer tissue (p = 0.0185, Student’s t-test)." (PMID 32629869, 2020). "In another experiments, we compared the secretion of AnxA2 in breast cancer cell lines with normal mammary epithelial cells." (PMID 33374917, 2020).
breast carcinoma (continued). "Proteomics analysis of exosomes from cultured breast cancer cells and sera of breast cancer patients identified AnxA2 as one of the vital metastatic proteins which plays an important role in angiogenesis and metastasis." (PMID 31992335, 2020). "Breast cancer cell lines with ANXA2 expression data available (n = 49) were first categorized according to positive or negative ER status according to previously published molecular characterization studies." (PMID 32629869, 2020). "The results of the present study, along with our previous study, clearly suggest that exo-AnxA2 derived from the cell culture supernatant or sera of the breast cancer patients contributes to the formation of new blood vessels." (PMID 31992335, 2020). "AnxA2 is overexpressed in malignancies, such as breast cancer and glioblastoma, and likely contributes to cancer progression in the context of an inflammatory microenvironment." (PMID 32575495, 2020). "We found that AnxA2 was significantly upregulated in tumor tissues and serum samples of breast cancer patients compared with normal controls." (PMID 33374917, 2020). "Our recent studies have identified annexin A2 (AnxA2), a 36-kDa calcium-dependent phospholipid-binding protein, as one of the most highly expressed proteins in breast cancer and breast cancer exosomes." (PMID 31992335, 2020). "Annexin A2, having satisfied these criteria and was chosen as a candidate protein to investigate how perturbing this elucidated network would affect breast cancer cell migration and invasion." (PMID 32629869, 2020). "Due to our accumulating evidence of Annexin A2′s importance in breast cancer progression in our in vitro cell models, we next investigated its expression in breast cancer patient tissue." (PMID 32629869, 2020). "These trends are further evidenced by querying the METABRIC (Molecular Taxonomy of Breast Cancer International Consortium) cohort for ANXA2 expression." (PMID 32629869, 2020). "The analysis of AnxA2 secretion and phosphorylation in a panel of breast cancer cell lines further suggest that the high secretion of AnxA2 from TNBC cells is primarily linked with the Tyr23 phosphorylation of AnxA2." (PMID 33374917, 2020). "The results of the present study demonstrated that the expression of serum AnxA2 is significantly elevated in TNBC compared to other subtypes of breast cancer patients." (PMID 33374917, 2020). "We demonstrated that Anxa2 Tyr23 phosphorylation is necessary for multidrug-resistant breast cancer invasion and metastasis." (PMID 31113450, 2019). "Annexin A2, which is highly expressed in breast-cancer derived exosomes, has also been reported to play a role in macrophage-mediated inflammatory response." (PMID 31555295, 2019). "In this study, we demonstrated that Anxa2 Tyr23 phosphorylation is required for MDR breast cancer invasion and metastasis." (PMID 31113450, 2019). "Rack1 is required for the invasive and metastatic potential of drug-resistant breast cancer cells through modulating Anxa2 phosphorylation." (PMID 31113450, 2019). "The interaction between Anxa2 and Rack1/Src is responsible for the association between MDR and invasive potential in breast cancer cells." (PMID 31113450, 2019). "Rack1 knockdown decreases Adriamycin-triggered Tyr23 phosphorylation of Anxa2 in drug-resistant breast cancer." (PMID 31113450, 2019). "Rack1 is required for the invasive and metastatic potential of MDR breast cancer cells through mediating the binding of Anxa2 to Src, thereby facilitating Anxa2 phosphorylation by Src kinase." (PMID 31113450, 2019). "In summary, these data suggested that Anxa2 tyrosine phosphorylation is required for the invasiveness of drug-resistant breast cancer cells." (PMID 31113450, 2019). "For example, knockdown of ANXA2 in breast cancer cells resulted in a more epithelial phenotype, in which cells were unable to undergo EGF-induced EMT." (PMID 29568351, 2018).
breast carcinoma (continued). "Upregulated expression of ANXA2 was observed in multiple cancers including epithelial ovarian cancer and breast cancer." (PMID 29568351, 2018). "Phosphorylated ANXA2 binds to actin filaments on cell membranes, and modulates cell scattering and cytoskeletal changes via actin remodeling in human breast cancer cells (SK-BR-3 and BT-474)." (PMID 29598816, 2018). "Recently, it was shown that MDR1 associated with the calcium-dependent phospholipid-binding protein Annexin A2 to promote invasion in multidrug-resistant breast cancer cells." (PMID 30356079, 2018). "Taken together, these results suggested that 2448 specifically binds to a unique glycan epitope on ANXA2 expressed on the cell surface of ovarian and breast cancer cells." (PMID 29568351, 2018). "AnxA1, AnxA2, and AnxA6 were the only annexins identified to be significantly associated with clinical outcomes of TNBC patients in comparison with all other breast cancer subtypes." (PMID 29416802, 2018). "The knockdown of annexin A2 and concurrent loss of S100A10 expression decreases the cell proliferation of invasive MDA-MB-435S breast cancer cells." (PMID 30572596, 2018). "Apart from the ability to select for undifferentiated hESC, 2448 was found to also bind on the surface of epithelial ovarian and breast cancer cells; and the antigen target of 2448 was identified as a glycosylated epitope on annexin A2 (ANXA2)." (PMID 29568351, 2018). "AnxA2, the annexin protein that has been studied in detail in breast cancer, has been shown to promote TNBC progression, through angiogenesis and metastasis." (PMID 29416802, 2018). "Previous studies have suggested that ANXA2 is highly upregulated in many malignant tumors, including breast cancer, renal cell carcinoma, colorectal cancer, hepatocellular carcinoma and pancreatic ductal adenocarcinoma." (PMID 28814318, 2017). "We previously showed that P-gp binds to Anxa2 and promotes the invasiveness of multidrug-resistant (MDR) breast cancer cells through regulation of Anxa2 phosphorylation." (PMID 27754360, 2016). "We previously reported that P-gp interacts with Anxa2 and promotes the invasiveness of MDR breast cancer cells by regulating Anxa2 phosphorylation." (PMID 27754360, 2016). "In this study, upregulated Anxa2 expression was significantly negatively correlation with low E-cadherin expression in breast cancer tissues and cell lines." (PMID 26307676, 2015). "Here, we investigated the relationship between Anxa2 protein expression and breast cancer prognosis by immunohistochemistry." (PMID 26307676, 2015). "Meanwhile, Anxa2 depletion significantly ablated pulmonary metastasis in a severe combined immunodeficiency mouse model of breast cancer." (PMID 26307676, 2015). "Overexpression of annexin A2 (Anxa2) is correlated with invasion and metastasis in breast cancer cells." (PMID 26307676, 2015). "In this study, breast cancer patients with upregulated Anxa2 exhibited poor overall and disease-free survival rates." (PMID 26307676, 2015). "Subsequently, a panel of human breast cancer cell lines was screened for Anxa2, EMT markers, and EGFR expression by Western blotting analysis." (PMID 26307676, 2015). "In human breast cancer tissues, Anxa2 was found to be selectively expressed in IDC and DCIS but undetected in normal ductal epithelium and hyperplastic tissues." (PMID 26307676, 2015). "Anxa2 knockdown significantly ablated pulmonary metastasis in an in vivo SCID mouse model of breast cancer." (PMID 26307676, 2015). "Taken together, these results strongly indicate that elevated expression of Anxa2 and EGFR has a direct association with EMT in breast cancer." (PMID 26307676, 2015). "Functional studies confirmed interaction of MIEN1 with AnxA2 at the membrane interface is necessary for activation of plasmin-plasminogen complex, thereby facilitating breast cancer cell migration and invasion." (PMID 26272794, 2015).